APOE (apolipoprotein E)
Diseases named in the same sentence as APOE in open-access papers (continued):
Sharing a sentence is not in itself a finding about the gene and the disease.
Cognitive impairment (continued). "In conclusion, total and isoform-specific apoE concentrations in CSF do not seem to be associated with AD diagnosis, cognitive impairment, or rate of decline." (PMID 32054532, 2020). "Recent evidence shows that APOE status influences cognitive impairment in T2DM patients." (PMID 32612525, 2020). "This review provides an overview of potential mechanisms that could account for aspects of cancer-related cognitive impairment, and how they could be affected by the APOE genotype." (PMID 33352780, 2020). "Patients in the CBS-AD group had a longer diagnostic latency, relatively benign clinical trajectory, greater cognitive impairment, and higher APOE-ε4 allele frequency than those in the CBS–non-AD group (AUC, 0.80-0.87; P < .05)." (PMID 31860007, 2020). "Similarly, an increased frequency of APOE ε2 (or decreased frequency of APOE ε4) leads to decreased levels of cognitive impairment, which raises questions regarding the impact of Aβ pathology on overall cognition in elderly subjects." (PMID 33287896, 2020). "Our study found the APOE ε4 carriers had a higher risk of cognitive impairment, and did not benefit from the protective effects of residential greenness, compared with the non-ε4 carriers." (PMID 31919381, 2020). "A plausible explanation of the protective effect of APOE*ε2 against AD may be that APOE*ε2 carriers have better baseline cognition, which sets a higher threshold for cognitive impairment." (PMID 33148290, 2020). "For this purpose, resting-state electroencephalography (EEG) activity was analyzed by computing Lempel-Ziv complexity (LZC) from 46 healthy control subjects, 49 mild cognitive impairment subjects, 45 mild AD patients, 44 moderate AD patients and 33 severe AD patients, subdivided by ApoE status." (PMID 32664228, 2020). "Additionally, ApoE-ε4 carriers with mild cognitive impairment (MCI) are more likely to have decreased REM sleep duration than non-carriers with MCI." (PMID 32645032, 2020). "In addition, studies show that APOE*ε2 protects against cognitive impairment in individuals over 90 years of age who have high levels of Aβ in the brain." (PMID 33148290, 2020). "We hypothesized that sex modulates the relationship between ApoE ε4 carrier status and brain tau deposition (a quantitative endophenotype in AD) in individuals with mild cognitive impairment (MCI)." (PMID 31410194, 2019). "However, reduced plasma apolipoprotein E levels have been considered a marker of progression of cognitive impairment independently of the APOE genotype." (PMID 30897703, 2019). "Previous studies have shown APOE4 mice have cognitive deficits or decreased neuronal complexity from as early as three months and these deficits remain at later ages such as 21 months, consistent with APOE genotype dependent deficits seen in our study." (PMID 31554665, 2019). "This may indicate that the effects of elevated BG on cognitive impairment vary in the different APOE genotype groups." (PMID 30984391, 2019). "AD develops as a result of multiple factors including aging over 65 and having apolipoprotein E (APOE) ε4 gene, family history, mild cognitive impairment (MCI), cardiovascular disease risk factors (e.g. smoking, obesity in midlife and diabetes, midlife hypertension) and lower educational attainment." (PMID 31998450, 2019). "Furthermore, higher levels of ApoE in the brain were able to induce abnormally phosphorylated tau protein resembling pre-neurofibrillary tangles and also cognitive impairment in mice." (PMID 30935111, 2019). "Studies of APOE ε4-targeted replacement mice proposed a clear link between early-life stress and cognitive impairment in middle-aged mice, but whether these observations are of relevance to humans needs to be confirmed." (PMID 28137305, 2017). "In this respect, anti-ApoE antibody may be developed as a potential treatment toward cognitive impairment." (PMID 28496408, 2017).
Cognitive impairment (continued). "However, as ApoE participates in the clearance of Aβ, it is now believed to be involved in the genesis of cognitive impairment." (PMID 28496408, 2017). "ABCA1 219K allele has been suggested to increase the ABCA1 protein function by accelerating cholesterol efflux, altering Aβ secretion, and influencing APOE metabolism, and any of which might be critical in the etiology of cognitive impairment." (PMID 28824418, 2017). "The younger cohort had a larger proportion of homozygote apolipoprotein E (APOE) ε4 allele carriers than the older cohort; however, APOE genotype was not a significant predictor of cognitive impairment in the multivariate models." (PMID 28859660, 2017). "But whether the cognitive impairment of ApoE-KO mice with high-fat diet had relation with active-AEP and the following truncated tau and whether 7,8-DHF could decrease tau truncation by inhibiting activation of AEP were still unknown." (PMID 27965573, 2016). "Other risk factors include family history, being an Apolipoprotein E-ε4 (APOE-ε4) allele carrier, mild cognitive impairment (MCI), cardiovascular disease risk factors (high cholesterol, type 2 diabetes, high blood pressure, smoking, obesity, etc), and traumatic brain injury 6-10." (PMID 28293044, 2016). "We also hypothesized that, comparing with C57BL/6 mouse, ApoE-KO mouse, with severe cerebrovascular atherosclerosis, expressed more tau pathology, which could aggravate cognitive impairment." (PMID 27965573, 2016). "To investigate whether amelioration of cognitive impairment in ApoE-KO mice correlated with 7,8-DHF treatment, we assessed the alteration of BDNF/TrkB/AKT pathway with western blotting." (PMID 27965573, 2016). "A detailed comparison of EFAD and APOE-TR mice may reveal whether Aβ accelerates the APOE4 and female sex driven cognitive deficits and changes in CV coverage." (PMID 27788676, 2016). "Whether tau pathology, like truncated tau and phosphorylated tau, could aggravate cognitive deficits of ApoE-KO mouse fed with western type diet was still unknown." (PMID 27965573, 2016). "Moreover, including age in the models highlighted the role of the other disease-related factors such as cognitive impairment and ApoE-e4 genotype." (PMID 26440606, 2016). "Some studies showed that the lower ApoE levels in individuals with AD and the high plasma ApoE levels in old age with cognitive impairment were not accounted for by the ApoEε4 allele." (PMID 26682220, 2015). "This is consistent with a possibly more pronounced contribution of heterogeneous vascular risk factors to WM damage and cognitive impairment in patients with AD without APOE ε4-mediated risk." (PMID 25984242, 2015). "For example, apoE-deficient mice display more severe brain edema, higher BBB permeability, and worse cognitive impairment after brain injury, while exogenous intraventricular infusion of apoE displays significant therapeutic effects after cerebral ischemia injury." (PMID 25844636, 2015). "Indeed, in this study apoE-related cognitive impairment correlates with a decrease in the levels of NMDR subunits and components of the signaling pathway (p-CaMK-II/p-CREB/BDNF)." (PMID 25871877, 2015). "As with non-AD patients, in APOE-TR mice, apoE4 is associated with cognitive deficits in both young (Morris water maze, Barnes maze) and older mice (Morris water maze, Y-maze)." (PMID 25871877, 2015). "Therefore, further research is needed to determine the influence of APOE and GSTM1/T1 polymorphism on cognitive impairment among a larger random sample of Chinese elderly." (PMID 26404360, 2015). "Actually, no consistent association of blood ApoE levels with cognitive impairment was seen when controlling for ApoE genotype." (PMID 26682220, 2015). "It would be interesting in future studies to investigate whether there is any change to S1P levels in the cerebrospinal fluid (CSF) of subjects with mild cognitive impairment or AD; and whether S1P levels in the CSF vary with APOE genotype." (PMID 24456642, 2014).
Cognitive impairment (continued). "Discussion: Both chronicity and emergence of objectively classified early cognitive impairment may be genetically heterogeneous phenomena, with influences from a panel of both normal cognitive aging (COMT) and AD-related (APOE) polymorphisms." (PMID 25249975, 2014). "A recent study of functional ability in amnestic mild cognitive impairment showed that patients carrying the APOE ε4 allele had more IADL deficits compared with non-carriers." (PMID 24099236, 2013). "Higher rates of depressive symptoms (OR = 1.41, 95%-CI = 1.02-1.95) and higher burden of the APOE-ε4 allele (OR = 3.29, 95%-CI = 1.51-7.40) predicted objective cognitive impairment, regardless of age, sex, years of formal education, time since infection, and medication for diabetes or hypertension." (PMID 40021517, 2025). "Cerebrospinal fluid (CSF) and/or plasma biomarkers, in combination with brain MRI, amyloid positron emission tomography (PET), and Apolipoprotein E (APOE) genotyping may assist in the earlier recognition of the disease and the detailed workup of patients with cognitive impairment." (PMID 40566003, 2025). "We tested whether the APOE GWAS signal for NPS was be mediated by cognitive impairment." (PMID 39974048, 2025). "Participants with cognitive impairment were more likely to be older, female, less educated, work in manual labor, have unhealthy dietary habits, smoke less, drink less, spend less time being sedentary, have functional limitations, and were more likely to be APOE ε4 carriers." (PMID 39789564, 2025). "Subsequently, ApoE−/− mice exhibiting cognitive impairment underwent a 10-week aerobic exercise regimen to assess whether this intervention could reduce aortic plaque area and alleviate cognitive deficits in the AS model." (PMID 40556958, 2025). "Although APOE ε4 is a known genetic risk factor, its association with CI was less clear in this study population, as a considerable proportion of ε4 carriers did not present cognitive impairment (p < 0.05)." (PMID 40429722, 2025). "However, the relationship among APOE, cognitive impairment, and apathy is uncertain." (PMID 39974048, 2025). "Therefore, these discrepancies in the relationship between APOE ε4 and p-tau181 may be partly attributable to differences in the study populations and the degree of cognitive impairment." (PMID 40725025, 2025). "Following up individuals after clinical conversion may produce modest quantitative shifts - such as stronger effects of brain atrophy, age × brain atrophy, and APOE ε4 on memory decline – consistent with established links among these measures and cognitive impairment." (PMID 41271752, 2025). "The impact of hormone replacement therapy on AD risk in postmenopausal women is inconsistent and may be related to APOE4 since it was reported to improve episodic memory and reduced the risk of cognitive impairment albeit only in APOE-ε4 non-carriers." (PMID 38414633, 2024). "Importantly, our discovery analysis demonstrated that these findings did not extend to APOEε3 homozygotes, suggesting that the biology linking these proteins to cognitive impairment may be influenced by APOE genotype." (PMID 39482741, 2024). "Associations between sleep characteristics and the odds of cognitive impairment, adjusted for age, sex, BMI, site, years of education, CESD depressive symptoms score, age difference from baseline to follow-up, alcohol use, and presence of the APOE e4 allele (N = 130)." (PMID 38903901, 2024). "APOE modifies microstructural patterns associated with aging and cognitive impairment, which may advance the development of biomarkers to distinguish microstructural changes characteristic of normal brain aging, APOE-dependent pathways, and non-AD etiologies." (PMID 38212861, 2024). "In addition, there is a significant interaction between APOE ε4 and sleep disorders, which may jointly lead to the appearance of cognitive impairment." (PMID 39639910, 2024).
Cognitive impairment (continued). "In addition, the contribution of ApoE 4 to modify the associations between GMV and cognitive impairment was investigated, suggesting a shift in the positive association between GMV and cognitive performance due to cholinergic neuronal dysfunction resulting from ApoE 4 status." (PMID 38376028, 2024). "In summary, we found that the carrying state of APOE ε4 can change the influence of daily life variables on cognitive impairment, and there may be a significant interaction between APOE ε4 and sleep disorders, which jointly promote the occurrence of cognitive impairment." (PMID 39639910, 2024). "Together, our findings indicate that microstructural signatures of APOE genotype emerge prior to cognitive impairment in patterns that may differ by sex, with entorhinal neurite loss as a potential preclinical AD biomarker, and WM microstructure associated with reduced AD risk." (PMID 38212861, 2024). "A correlation has also been found between worse subjective cognitive impairment scores and a reduction in RNFL volume in a 27-month longitudinal study among subjects with a first-degree family history of AD, carriers of any ɛ4 allele for ApoE, and subjective cognitive impairment." (PMID 37509663, 2023). "Consistent with prior research, we observed that, relative to those with no APOE-ε4 alleles, risk for cognitive impairment increased as APOE-ε4 allele count increased from one allele (IRR = 1.24, 95% CI [1.15–1.34], P<0.001) to two (IRR = 1.57, 95% CI [1.26–1.96], P<0.001) (Model 2.1)." (PMID 38048316, 2023). "The WMH and APOE e4 alleles may not directly influence each other but both contribute to cognitive impairment, especially memory loss, in AD dementia." (PMID 36864910, 2023). "Our results contribute to potential mechanisms for sex differences in cognitive impairment with a novel finding of twice the annual choroid plexus enlargement in females and provide putative support for CP-related mechanisms of cognitive deterioration and its relationship to ApoE E4." (PMID 36970283, 2023). "Full adjustment for the extended panel of environmental risk factors had similarly negligible impact (Model 2.4) suggesting that the monogenic risk for cognitive impairment conferred by APOE-ε4 genotype is independent of Lifetime incarceration and key environmental risks." (PMID 38048316, 2023). "However, our results suggest that the influence of APOE ε4 on cognitive impairment may be more nuanced and possibly modulated by other factors such as depression and physical activity." (PMID 38026513, 2023). "To determine whether apoE has isoform-dependent effects on hAPP/Aβ-induced behavioral alterations and cognitive impairments in aged female and male mice at 18 months of age, we crossed APP NL-F KI with E2, E3, and E4 mice to generate NL-F/E2, NL-F/E3, and NL-F/E4 mice." (PMID 35299942, 2022). "Furthermore, compared to control therapy, sevoflurane anesthesia might have exacerbated cognitive impairment in both WT and ApoE mice (p < .05 vs." (PMID 35810473, 2022). "In the present study, we determined the effect of APOE genotype on the association between myo-inositol and both amyloid-β and tau deposition quantified by PET in 428 cognitively unimpaired elderly and patients with mild cognitive impairment from the Swedish BioFINDER-2 cohort." (PMID 35702728, 2022). "To determine whether apoE has isoform-dependent effects on hAPP/Aβ-induced behavioral alterations and cognitive impairments in adult female and male mice at 6 months of age, we crossed APP NL-G-F mice with E2, E3, and E4 mice to generate NL-G-F/E2, NL-G-F/E3, and NL-G-F/E4 mice." (PMID 35299942, 2022). "Here, we have tested the hypothesis that APOE ε4 allele count increases sleep disturbance in people with and without cognitive impairment, independently of its influence on the two major hallmark AD pathologies (Aβ plaques and tau neurofibrillary tangles)." (PMID 35354468, 2022).
Cognitive impairment (continued). "Therefore, to determine whether apoE has isoform-dependent effects on hAPP/Aβ-induced behavioral alterations and cognitive impairments in adult female and male mice at 6 and 18 months of age, we crossed AppNL–G–F and AppNL–F mice with E2, E3, and E4 mice." (PMID 35299942, 2022). "However, the mechanisms on the effect of APOE ε4 on cognitive impairment are not fully understood." (PMID 35160273, 2022). "In combination with the ApoE ε4 genotype results, our findings on distinct neural correlates of memory decline between carriers and non-carriers provide new potential targets for the exploration of biomarkers and neuromodulation of cognitive impairment in the future." (PMID 35693343, 2022). "While previous studies have reported significant cognitive impairment in ApoE variants carriers compared to non-carriers across a range of cognitive domains, but the results of studies conducted in all these areas have been inconclusive, which were likely to be related to ethnic difference." (PMID 35351068, 2022). "as we did not see an association with APOE ε4 and cognitive impairment, which might be explained by the fact that we studied a pathologically confirmed amyloid-negative cohort." (PMID 34353357, 2021). "Of the three major ApoE isoforms ApoE2, ApoE3 and ApoE4, the E4 isoform is strongly associated with the onset of AD and disease progression, thus reducing the ApoE4 level is hypothesized to induce reduction of Aβ accumulation and attenuation of cognitive deficits." (PMID 34016162, 2021). "Regarding potential underlying mechanisms, APOE ε2+ carriers may show protective effects by using compensatory mechanisms; specifically, recent study showed that amnestic mild cognitive impairment adults had increased functional connectivity in the entorhinal cortex network for APOE ε2+ carriers." (PMID 34603005, 2021). "In addition, a healthier lifestyle was associated with lower odds of cognitive impairment regardless of APOE genotype." (PMID 34061824, 2021). "Besides, the developments of cognitive impairment and depressive symptoms are the results of GxE interactions, especially social factors, but studies examining the interactions between social vulnerability and ApoE and 5-HTTLPR genotypes are scarce." (PMID 34647905, 2021). "Genetic polymorphisms in select genes, including APOE (apolipoprotein E), COMT (Catechol-O-Methyltransferase), MDR1 (multi-drug resistance 1), BDNF (brain derived neurotrophic factor), and GST (glutathione-S-transferase), have been associated with vulnerability to cognitive impairment." (PMID 33731765, 2021). "Another plausible explanation could be that APOE ε4 carriers who have not progressed to cognitive impairment during the risk age range of 65–75 years, might possess protective genetic or lifestyle factors that delay that progression." (PMID 32464432, 2020). "APOE ε4 carriers with AD showed altered concentrations of proteins involved in the complement pathway and glycolysis when cognition was normal and lower concentrations of proteins involved in synapse structure and function when cognitive impairment was moderately severe." (PMID 32460813, 2020). "This study also investigated whether this association was altered by sex, age, education level, or Apolipoprotein E (APOE) genotype, and estimated the relationship between plasma Aβ and cognitive disorder and cardio-cerebrovascular diseases during a 2-year follow-up." (PMID 33061905, 2020). "Similarly, an increased frequency of APOE ε2 or decreased frequency of APOE ε4 may lead to decreased levels of cognitive impairment, which raises questions regarding the impact of Aβ pathology on overall cognition in elderly subjects." (PMID 33287896, 2020). "Third, we could not adjust for the apolipoprotein E (APOE) status, while APOE4 is associated with increased risk of cognitive impairment, so associations of dietary patterns with cognitive impairment may potentially be overestimated." (PMID 29642510, 2018).